TNF (tumor necrosis factor)
Diseases named in the same sentence as TNF in open-access papers (continued):
Sharing a sentence is not in itself a finding about the gene and the disease.
cancer (continued). "Given these regional differences and the relatively young age of Asian patients with AS, this study aimed to evaluate age-specific cancer risks associated with TNF inhibitor therapy and to identify factors contributing to malignancy development in Korean patients with AS." (PMID 41302997, 2025). "Interestingly, previously, we have reported that C rs1799724 variant of the TNF gene was related to the SSc development, while CT rs1799964 and AG rs361525 genotypes were associated with cancer susceptibility in those patients." (PMID 41272109, 2025). "Positively enriched hallmark gene sets that distinguished the cancer microenvironment include signaling networks such as TNF-alpha signaling; metabolism-associated processes such as glycolysis; and microenvironmental conditions that include hypoxia, adipogenesis, and angiogenesis." (PMID 39511408, 2025). "Studies encompassing patients with various cancer diagnoses and treatment regimens indicate associations between plasma cytokine levels and cognition, particularly the proinflammatory cytokines interleukin (IL)−6 and tumor-necrosis factor (TNF)-α." (PMID 40597835, 2025). "TNF-α antagonists are effective in treating IBD but may also elevate cancer risk due to immunosuppression." (PMID 39968296, 2025). "TNF-α is another major inflammatory cytokine implicated in cancer." (PMID 41007766, 2025). "Key cytokines implicated in cancer cachexia include IL-6, TNF-α, TGF-β, INF-γ and MIC-1/GDF15." (PMID 40519290, 2025). "However, the protein expression appears to be under the influence of tumour necrosis factor-α (TNF-α), a major inflammatory cytokine implicated in many human cancers." (PMID 40425987, 2025). "Furthermore, we observed the upregulation of various cancer-associated hallmarks in cells expressing these high-risk genes, including TNF-alpha, UV response, angiogenesis, MYC, and KRAS." (PMID 40362553, 2025). "While our cytokine array results demonstrate that EMD-CM from cancer cells primarily induces M2 polarization in macrophages, we also observed an increase in cytokines traditionally associated with M1 polarization, such as TNF-α, IL-1β, and IL-6." (PMID 39941817, 2025). "TNF exacerbates oxidative stress, which damages DNA and increases cancer risk." (PMID 40547917, 2025). "Notably, 176 regions that were hypomethylated in cancer were remethylated after curcumin treatment, including the tumor necrosis factor (TNF) gene, suggesting a reversal of tumor-associated epigenetic changes." (PMID 40969596, 2025). "Overall, the BME extract and its active phytochemicals (compound A) with a multi-targeted approach exhibited higher cytotoxic and antioxidative potential by targeting cancer-causing proteins (TNF-α, TGF-βR1 and iNOS) having established role in initiation and progression of HCC." (PMID 40294146, 2025). "Moreover, TNF‐producing Tregs have been associated with a Th17‐like phenotype in various pathological contexts, including cancer." (PMID 40977146, 2025). "While suppressing cytokines like IL-6 and TNF-α can be beneficial, over-suppression may lead to immunosuppression and increased susceptibility to infections, thus complicating treatment in cancer patients." (PMID 40544399, 2025). "Given the high levels of Vim and low levels of α-SMA, these cells may have an inflammatory phenotype similar to cancer-associated fibroblasts (CAFs) that differentiate under TNF-α + IL-1β stimulation." (PMID 39808504, 2025). "TNF-α is closely associated with the development of chronic inflammation and cancer." (PMID 40959697, 2025). "In this long-term Korean cohort of patients with AS treated with TNF inhibitors, age was the only consistent independent risk factor, and stratified analyses demonstrated that the factors associated with cancer occurrence differed between younger and older patients." (PMID 41302997, 2025).
cancer (continued). "Moreover, VHH can be fused with cytokines to construct immunocytokines, such as IL2 and TNF-α, for anti-cancer treatments, which can overcome the adverse effects caused by using cytokines as monotherapy." (PMID 40358697, 2025). "In association with IFN‐γ, TNF induces senescence in cancer cell lines." (PMID 40297580, 2025). "LCN2 is associated with UC duration and cancer risk, which may be regulated by IL-17A, IL-22, and TNF-α." (PMID 40153427, 2025). "The authors have shown that the connections between IL-6, CRP, and TNF-α and cancer risk may be site-specific." (PMID 40584290, 2025). "TNF -α is a proinflammatory cytokine frequently associated in the promotion of cancer growth." (PMID 40903738, 2025). "Insufficient data exist on csDMARDs such as methotrexate, but one retrospective study in ICI-IA found that use of TNF or IL-6R inhibitors was associated with faster time to arthritis improvement, but may be associated with shorter time to cancer progression." (PMID 40774545, 2025). "Furthermore, we observed upregulation of the TNFα-NFκB and Kras signaling pathways in the C1 subtype, which have been implicated in the progression and drug resistance of various cancers." (PMID 38767747, 2024). "Furthermore, the loss of Mgat5 glycans can sensitize cancer cells to either TNF-α– or TRAIL-mediated cell death through necroptotic and/or apoptotic pathways." (PMID 38912584, 2024). "Indeed, levels of H3Cit in cancer patients have been shown to have a positive association with TNFα, IL-6, and IL-8, indicating a relationship between the expression of these pro-inflammatory cytokines and the release of H3Cit." (PMID 38744744, 2024). "Interestingly, the cancer cell apoptosis and death caused by M-DCsTNF CM plus SM-164 were completely blocked by anti-TNF antibody." (PMID 39105847, 2024). "Cyclooxygenases-2 antagonists may increase the susceptibility of cancer cells to TNF-α-induced cell death by inducing the production of reactive oxygen species or inhibiting the NF-κB pathway." (PMID 39830670, 2024). "Moreover, the KEGG-enriched IL-17 signaling pathway and TNF signaling pathway, are closely associated with cancer development." (PMID 39689118, 2024). "Anti-TNF therapy has also been shown to increase the risk of cancer." (PMID 39120313, 2024). "Additionally, inflammation-inducing cytokines like TNF-α and IL-6 play a critical role in causing anemia in cancer patients, not only by promoting inflammation but also by influencing genes such as GATA-1 and GATA-2, which regulate red blood cell production." (PMID 39830670, 2024). "Once LAB colonizes in GC, it can potentially promote GC via 4 mechanisms: 1) via impact the release of interleukin-1β/17 A/22, 2) via IL-17RC/NF-ᴋB/NOX1 pathway, 3) via gastric inflammatory and cancer-associated genes TNF-α/Ptger4/Tgf-β, 4) via N-nitroso compounds and 5) ROS." (PMID 38075398, 2024). "Furthermore, cancer-associated symptoms involve TNF-alpha and IL-1β, which are key orchestrators of chemotherapy-related cardiomyopathies (CTRCDs), myocarditis, vasculitis, and cardiac fibrosis." (PMID 39200115, 2024). "In addition, the increased TNF-α serum levels in cancer patients are associated with adverse disease outcomes." (PMID 39408920, 2024). "The association between the use of TNF-α inhibitors and cancer development has been debated." (PMID 39046819, 2024). "Several studies have confirmed the protective role of γδ T cells in transplantable or spontaneous cancer models, and their antitumor function is closely associated with their production of interferon γ (IFNγ) and tumor necrosis factor (TNF), and/or their cytotoxic potential." (PMID 39309735, 2024). "An increased level of sleep-mediating cytokines, such as IL-6, TNF-α, and sTNF-R in cancer patients could cause impaired sleep quality." (PMID 38257176, 2024).
cancer (continued). "Additionally, MLN4924 can enhance the susceptibility of certain cancer cells to tumor necrosis factor-α (TNF)-induced cell death, suggesting its capacity to suppress the stemness of cancer cells." (PMID 38398217, 2024). "Furthermore, deleterious mitochondrial mutations are associated with the overexpression of genes involved in cancer signaling pathways, such as the TNFα pathway, OxPhos, and protein secretion pathways." (PMID 39179991, 2024). "Tumor necrosis factor (TNF) is a pro-inflammatory cytokine associated with different cancer types." (PMID 38543009, 2024). "In turn, as we found in this report, AG and GC rs361525 genotypes may be related to higher serum TNF alpha, leading to increased cancer risk in this mechanism." (PMID 38051374, 2024). "The stimulation of PPAT exosomes by PC-3 CM induced the secretion of the bone-bridging protein, TNF-α, and IL-6, which are associated with cancer progression, upregulation of bone-bridging protein expression by 13-fold, and decreased expression of the protective adipokine lipocalin." (PMID 38164282, 2024). "Malignancies are associated with elevated levels of circulating cytokines, such as tumor necrosis factor and IL-1, which can cause local damage to valve leaflets at the endothelium level, triggering platelet and fibrin deposition and instigating vegetation formation." (PMID 38952603, 2024). "Pro-inflammatory cytokines such as TNF-α and IL-6 are linked to cancer." (PMID 39120359, 2024). "The results of GSEA demonstrated that DEGs mainly enriched in several pathways associated with immune response, cancer proliferation and metastasis, such as Interferon alpha/gamma response, TNFα signaling, MYC/E2F targets, and epithelial mesenchymal transition." (PMID 39376555, 2024). "Therefore, this review aims to discuss mechanisms of sphingolipid involvement in TNF-α-resistance in cancer cells and provide insights into the association of immune evasion with regards to SphK/S1P/S1PR axis." (PMID 38698424, 2024). "The inflammatory mechanism is not specific to bacteria, in almost all mechanisms of bacterial inflammation and cancer, the implicated bacteria reside in the host for many years, accompanying this response to inflammation is the antiviral action of IL-1β, TNF-α and IFN-γ." (PMID 39608222, 2024). "The impact of TNF-α polymorphisms has been explored across various cancer types." (PMID 38339076, 2024). "This study has uncovered a hitherto unknown mechanism involving the induction of mesenchymal reprogramming by the synergistic action of IL‐17A and TNF produced by Th17 cells, which renders the mesothelial monolayer susceptible to cancer cell adhesion." (PMID 38566518, 2024). "Additionally, STAT3, a transcription factor associated with cancer development, acts as a crucial mediator of TNF pathway activation." (PMID 39586790, 2024). "In T cells, TNF has been associated with dysfunction during chronic viral infection and cancer through upregulation of programmed cell death protein 1 (PD-1) and T cell immunoglobulin and mucin domain-containing protein 3 (Tim3), as well as impairment of cytokine production." (PMID 39543125, 2024). "Administration of JAK inhibitors in patients with RA was associated with elevated risk of major adverse CVD events, cancers and several adverse events compared to a TNF inhibitor, although the exact mechanisms of action on the cardiovascular system remain under investigation." (PMID 39463875, 2024). "It is well known that TNF-α is involved in the maintenance and homeostasis of the immune system and is closely associated with cancer development, while NF-κB is the major downstream target of TNF-α signalling, which highlights the importance of the TNF/NF-κB signalling pathway in immune activity." (PMID 39000093, 2024).
cancer (continued). "Here, we demonstrate that dual treatment with IAP and WEE1 inhibitors sensitizes both HPV-negative and HPV-positive HNSCC cells to both TNFα-dependent and radiation-associated cell death, demonstrating a potential therapeutic combination to treat these cancers." (PMID 36831373, 2023). "TNF can cause the death of cancer cells, making it a potential cancer treatment." (PMID 36874133, 2023). "In a transgenic INS-GAS mouse model, the gastric lesions instigated by the overgrowth of Lactobacillus murinus ASF361 were found to be correlated with the robust expression of molecules associated with gastric inflammation and cancer, including TNF-α, Ptger4, and TGF-β." (PMID 37583514, 2023). "Immunologically, Decitabine induces natural killer cells (NK cells) proliferation and can also differentiate naive T cells into effector T cells (CD8+ T-cells), which also secrete cytokines such as interferon-γ (IFN-γ) and tumor necrosis factor-α (TNFα), eventually causing cancer cell death." (PMID 37107631, 2023). "Moreover, a recombinant variant of adenovirus expressing TNF-α displayed cancer-eradicating potency by elevated apoptosis and necrosis with an enhanced level of cytotoxic T cells." (PMID 37112810, 2023). "For example, from a disease-specific point of view, CD53 is upregulated in atherosclerotic plaques and during coronary revascularization and is implicated in cancer surveillance and regulation of innate circulating tumor necrosis factor alpha (TNFα) levels in humans." (PMID 36581203, 2023). "This is significant because TNFα is associated with MCF-7 cancer cell lines." (PMID 37745072, 2023). "Whether TNFα-antagonists increase the risk of new/recurrent cancer in IBD patients with a diagnosis of cancer is being investigated." (PMID 37113615, 2023). "In addition to chemokines, inflammatory cytokines, including interleukin (IL)-17, IL-1β, and tumor necrosis factor (TNF), have all been implicated in neutrophil mobilization and recruitment to the cancer site." (PMID 37444436, 2023). "Indeed, we highlighted three pan-cancer NFκB/TNF hallmark genes (EGR1, JUNB, and ZNF36) and identified four candidates (SRGN, CCN2, TNFRSF12A, and ZFP36L1) that are highly potentially involved in NFκB/TNF pathways in various cancers." (PMID 37475016, 2023). "However, it is important to note that most data are from patients starting thiopurine or anti-TNF more than 5 years after cancer resolution and in patients with a low risk of cancer recurrence." (PMID 36983432, 2023). "Accordingly, blocking TNF-α-mediated weight loss could be a potential pharmacological option for treating cancer cachexia." (PMID 37600065, 2023). "Produced predominantly by macrophages, TNF-α acts to reinforce and maintain programmed death-ligand 1 protein expression and plays a role in modulating cytotoxic T cell activation, cumulatively resulting in cancer-associated immunosuppression." (PMID 39534571, 2023). "This has prompted a theoretical concern that inhibiting TNF-alpha may cause recurrence or rapid tumour progression in patients with cancer." (PMID 36831424, 2023). "A strong increase was observed in the serum levels of proinflammatory cytokines in rats treated with DEN, and these results were associated with cancer and inflammation (especially TNF-α and IL-6), which have been documented to be increased after the administration of DEN27." (PMID 36949140, 2023). "In addition, IL-8 is one of the most significant activating chemokine of cancer-associated cells, along with TNF-α and IL-6, which contribute to the proinflammatory profile of the TME in CRC patients." (PMID 37760840, 2023). "Moreover, the DDS caused an increase in the expression of pro-apoptotic genes in cancer cells and a decrease in the expression of the gene encoding the pro-inflammatory cytokine tumor necrosis factor α (TNF-α)." (PMID 37514058, 2023).
cancer (continued). "In this regard, it has been reported that anti-TNF agents may increase the risk of serious infections, as well cancer risk." (PMID 37407724, 2023). "IL-6 and TNFα have both been implicated in cancer cachexia, and efforts to block these cachexins may also improve responses to cancer-directed therapies." (PMID 37461742, 2023). "Using a gene set enrichment analysis of publicly available gene expression data from 161 newly diagnosed pediatric ALL patients, we found the Tumor necrosis factor α (TNF-α) signaling pathway via NF-κB to be the most enriched Cancer Hallmark in MTX-poor-responder patients." (PMID 37895229, 2023). "On the contrary, anti-TNFα treatment for auto-immune conditions may actually increase the risk of cancer, but more studies are needed to confirm this hypothesis." (PMID 37958474, 2023). "Notably, patients treated with JAK inhibitors were found to have an increased risk of cancer compared to those receiving TNF-α inhibitors." (PMID 38276003, 2023). "TNF-α is associated with acute and chronic inflammation and inflammation related to cancers." (PMID 36899319, 2023). "Particular attention should also be given to male CD patients below 30 years of age, in whom the thiopurine plus anti TNF combination has been shown to increase the risk for hepatosplenic T-cell lymphoma—a very rare and aggressive cancer—if used for more than 2 years." (PMID 37370740, 2023). "Visceral adipose tissue can promote cancer progression by inducing pro‐inflammatory adipokines such as tumor necrosis factor, which may partially explain why VSR is associated with resistance to anticancer agents and prognosis." (PMID 37184128, 2023). "However, more recent inhibitors have been discovered through various means, which not only reduced TGM-2 but also other factors such as MMP9, TIMP1 and 2; TNF-α and β, which increases cancer cells’ susceptibility to chemotherapy and inflammation." (PMID 37509081, 2023). "Biologically, the role of TNF-alpha in cancer progression remains unclear and has been linked to both cancer-suppressing and -promoting pathways." (PMID 36624408, 2023). "Additionally, numerous investigations have revealed that TNF plays an oncogenic function in cancers linked to inflammation." (PMID 36874133, 2023). "Although nitic oxide (NO), reactive oxygen species (ROS), IL-1β and TNF-α mediated cell death has been studied in cancer cells and may be associated with ICD induction, this cell death mechanism has not yet been elucidated in macrophage mediated cell death." (PMID 38077402, 2023). "This could be due to TNF-α’s ability to synergistically act with some bioactive compounds loaded on the iron oxide nanoparticle to cause cancer cells to undergo apoptosis." (PMID 36234520, 2022). "TNF was a significant mediator of inflammation associated with malignancy and has been discovered as a crucial player in the cytokine network outside of the cancer area." (PMID 36276869, 2022). "In addition to this, a meta-analysis of nine clinical trials shows a three times higher risk (OR 3.3 with CI 95%) of developing a malignancy in patients treated with anti-TNF-α vs. control; the risk is proportional to the dose administered." (PMID 35563587, 2022). "In addition, as a key necroptosis-associated molecule, TNF is reported to increase the sensitivity of many cancer types to doxorubicin." (PMID 35748782, 2022). "However, TNF-α was implicated in the induction of chemo-resistance, promoting invasion, and increasing the risk of metastasis in several cancers." (PMID 35406450, 2022). "One of the clinical trials investigating a TNF inhibitor (Etanercept, a recombinant fusion protein of TNF-α type II receptor) to treat cancer anorexia/weight loss syndrome in patients with solid tumor malignancies did not improve the outcomes of weight, appetite, or survival." (PMID 35159388, 2022).